RNU6-934P (RNA, U6 small nuclear 934, pseudogene)
Gene: Small nuclear RNA gene on chromosome X (101,325,404 to 101,325,510, forward strand). Ensembl gene ENSG00000202024.
Homologues: Orthologues: chimpanzee U6 (97% identical), macaque U6 (95% identical), dog U6 (81% identical), mouse Gm25322 (80% identical), dog U6 (79% identical), guinea pig U6 (78% identical), rabbit U6 (75% identical), dog U6 (74% identical), pig U6 (72% identical). Paralogues in human: RNU6-83P (86% identical), RNU6-774P (85% identical), RNU6-10P (84% identical), RNU6-1209P (84% identical), RNU6-1309P (84% identical), RNU6-46P (84% identical), RNU6-560P (84% identical), RNU6-86P (84% identical), RNU6-1113P (83% identical), RNU6-116P (83% identical), RNU6-11P (83% identical), RNU6-24P (83% identical), and 1289 more.